WDR5 (WD repeat domain 5)
Diseases named in the same sentence as WDR5 in open-access papers (continued):
Sharing a sentence is not in itself a finding about the gene and the disease.
gastric cancer (26 papers, 2015 to 2025). A primary or metastatic malignant neoplasm involving the stomach. "The lncRNA BDNF-AS/WDR5/FBXW7 axis modulates ferroptosis in gastric cancer by impacting the ubiquitination of voltage-dependent anion channel 3 (VDAC3), thereby mediating peritoneal metastasis of gastric cancer." (PMID 39827195, 2025). "WDR5 was found to promote cell proliferation through inducing H4K3me3 on the Cyclin D promoter to activate its expression in gastric cancer." (PMID 35371306, 2022). "Based on the studies and the results of molecular docking, it can be concluded that with the receptors of hCA IX, MMP-2, gastric cancer, blood cancer WDR5, and HCC, the compound derived from CM, that is, OHC, tends to show the best activity." (PMID 34452553, 2021). "The specific cancer types used in the present study were gastric cancer (urease), blood cancer (WDR5), HCCs, and pancreatic cancer (NHERF1)." (PMID 34452553, 2021). "Gastric cancer-associated WDR5 and KAT2A binding lncRNA (GCAWKR) modulates the affinity for WDR5/KAT2A complexes in the promoter region of target genes." (PMID 32429086, 2020). "Previous work has shown that the lncRNAs GClnc1 and GCAWKR can serve as scaffolds for KAT2A and WDR5 in gastric cancer, and can thereby serve as positive regulators of this enzyme." (PMID 31320749, 2020). "Cyclin D1 was detected to mediate cellular cycle change and proliferation guided by WDR5 in gastric cancer." (PMID 30974047, 2019). "Mechanistically, in gastric cancer cells, WDR5 induces histone H3K4 trimethylation at the Cyclin D1 gene promoter and Cyclin D1 gene transcription, leading to cancer cell proliferation." (PMID 30488017, 2018). "In bladder and gastric cancer, WDR5 increases the transcription of multiple cyclin proteins and stem cell-associated genes via increased H3K4Me3." (PMID 29925347, 2018). "The lncRNA GClnc1 is up-regulated in human gastric cancer tissues, and WDR5 binds GClnc1 to regulate the transcription of oncogenes, such as SOD2, and consequently induces gastric cancer cell proliferation, invasion and metastasis." (PMID 30488017, 2018). "For example, liu and colleagues found that over-expressed lncRNA HOXA11-AS promotes gastric cancer cells migration, invasion and metastasis in vivo through interacting with WDR5 and activating β-actinin transcription." (PMID 29152119, 2017). "The BDNF-AS/WD repeat domain 5 (WDR5)/F-box and WD repeat domain-containing 7 (FBXW7) axis regulates ferroptosis in gastric cancer cells by affecting the ubiquitination of voltage-dependent anion channel 3 (VDAC3)." (PMID 38481525, 2024). "GClnc1 acts as a modular scaffold for WDR5 (WD repeat domain 5) and KAT2A (Lysine Acetyltransferase 2A) to specify the histone modification pattern, thus promoting gastric cancer cell proliferation and invasiveness." (PMID 29970131, 2018). "WDR5 has been shown to cooperate with HOTTIP to promote HOXA9 in prostate and pancreatic cancer and HOXA13 expression in esophageal and gastric cancer cells by increasing H3K4Me3 on their promoters." (PMID 29925347, 2018). "Mechanistically, GClnc1 binds to WDR5 and KAT2A histone acetyltransferase, acts as a modular scaffold of WDR5 and KAT2A complexes, coordinates their localization and consequently alters gastric cancer proliferation, migration and invasion." (PMID 29113415, 2017). "In the present study, we showed that components of WRAD (WDR5, RBBP5 and ASH2L) can inhibit proliferation of gastric cancer cells, suggesting that DPY30 act through the increased H3K4MT activity." (PMID 26147337, 2015). "Besides, TCF3 can also be transcriptionally active WDR5 and involved in miR-17-5p and HOXA11-AS activation, which results in poorer prognosis in gastric cancer." (PMID 36829181, 2023). "It remains to be elucidated whether the currently observed H. pylori-heparanase axis involves WDR5 induction and H3K4 methylation, given their important epigenetic roles in the progression of various cancers including gastric cancer." (PMID 34220822, 2021).
gastric cancer (continued). "Another study demonstrated that gastric cancer-associated lncRNA1 (GClnc1) could act as a scaffold lncRNA linking WDR5 and KAT2A, triggering proliferation, invasion and metastasis by activating SOD2 in GC." (PMID 36419649, 2022).
prostate carcinoma (22 papers, 2015 to 2026). A carcinoma that arises from epithelial cells of the prostate gland. "The MLL complex and its association with WDR5 shows that SETD1A also plays an important role in prostate cancer, especially in the progression of mCRPC." (PMID 32629770, 2020). "Given these similarities and the importance of WDR5 in prostate cancer, we are interested in understanding the association between WDR5 expression and some phenotypic parameters in breast cancer." (PMID 26355959, 2015). "For instance, WDR5 is abundantly expressed in prostate cancer and conduces to androgen-induced tumor cell proliferation." (PMID 38115111, 2023). "First, to further determine the clinical relevance of WDR5 in prostate cancer, we analyzed the expression of WDR5 in 262 archived human paraffin-embedded prostate cancer tissues from two cohorts (cohort 1 and cohort 2) using immunochemistry." (PMID 33754029, 2021). "Aberrant expression of WDR5 was demonstrated in some cancers such as bladder cancer, leukemias and prostate cancer." (PMID 33754029, 2021). "WDR5 has been shown to be overexpressed in prostate cancer and involved in the proliferation of androgen-dependent prostate cancer cells." (PMID 33302406, 2020). "WDR5 is over-expressed in human prostate cancer tissues, induces prostate cancer cell proliferation, and drives castration resistance in prostate cancer cells." (PMID 30488017, 2018). "WDR5 has been previously reported to be overexpressed in prostate cancer and WDR5 expression is critical for proliferation of tumour cells." (PMID 26355959, 2015). "Given the similarities between breast and prostate cancers, we explore the potential prognostic value of WDR5 gene expression on breast cancer survival." (PMID 26355959, 2015). "Furthermore, the level of WDR5 expression is higher in prostate cancer than healthy prostate tissue; its interaction with androgen signaling, infers its purpose in the acceleration of prostate cancer cell proliferation." (PMID 37349324, 2023). "Twist1 regulates WDR5-Hottip-mediated Hoxa9 chromatin to promote prostate cancer metastasis." (PMID 36639679, 2023). "To investigate whether WDR5 was involved in the immunomodulatory in prostate cancer, we firstly evaluated the correlation between WDR5 and PD-L1 by immunochemistry." (PMID 33754029, 2021). "Notably, PKN1 regulates endometrial cancer cell proliferation by modulating TGFβ and epidermal growth factor (EGF) dependence, promotes prostate cancer cell proliferation through WDR5 (WD repeat-containing protein 5)." (PMID 28222172, 2017). "Moreover, WDR5 is overexpressed in prostate cancer and promotes proliferation upon androgen stimulation." (PMID 25656485, 2015). "WDR5 has been reported to be over-expressed in prostate cancer and is identified as a critical epigenetic integrator of histone phosphorylation and methylation, as well as a major driver of androgen-dependent prostate cancer cell proliferation." (PMID 26355959, 2015). "WDR5 is a core component of the human mixed lineage leukemia-2 complex, which plays central roles in ER positive tumour cells and is a major driver of androgen-dependent prostate cancer cell proliferation." (PMID 26355959, 2015). "In prostate cancer, TNK2 participates in a feed-forward epigenetic circuit involving ACK1/pY88-H4/WDR5/MLL2/AR and is necessary for malignant cancer." (PMID 34421982, 2021). "For instance, WDR5 has been found to be overexpressed in a number of cancers, including AML, neuroblastoma, prostate cancer, CRC, and bladder cancer." (PMID 33302406, 2020). "Recently, WDR5, a subunit of the SET1/MLL (mixed lineage leukemia) complex, has been suggested as a major driver of AR-dependent prostate cancer and has been shown to interact with H3T11P to guide MLL1 to the AR target gene site and promote H3K4me3." (PMID 32629770, 2020).
prostate carcinoma (continued). "In prostate cancer, HOTTIP forms a complex with the transcription factor TWIST1 and with WDR5 and produces upregulation of HOXA9 levels through chromatin regulation which correlates with an aggressive cellular phenotype." (PMID 30819158, 2019). "By forming a protein complex with TWIST1, WDR5 induces HOXA9 gene transcription, prostate cancer cell migration, invasion, and metastasis." (PMID 30488017, 2018). "Selected ARA-lincRNAs are neighbors of protein-coding genes WDR5, ZNF706, TFRC, and FLNA, which have been described as up-regulated in prostate cancer, and of CENPH and RAB11FIP3, which have been shown to play a role in many other types of cancer." (PMID 29875794, 2018). "In contrast, WDR5, a component of WRAD complex, has been reported to act as an oncoprotein in prostate cancer, in which it is overexpressed and crucial for the androgen-induced proliferation of tumor cells." (PMID 26147337, 2015). "The ectopic expression of WDR5 and negative correlations between WDR5 and prognosis are reported in several cancer types including prostate cancer, bladder cancer, cholangiocarcinoma, breast cancer and colorectal cancer." (PMID 36249032, 2022). "WDR5 also binds to ACK1-mediated H4Y88ph and directs KMT2D to the promoter of the androgen receptor gene, thereby promoting its expression in castration-resistant prostate cancer." (PMID 33302406, 2020). "Moreover, HOTTIP modulates cancer stem cell properties by binding WDR5 and activating HOXA9, which enhances the Wnt/β-catenin pathway in prostate cancer stem cells." (PMID 30819158, 2019).
bladder cancer (20 papers, 2013 to 2026). "Through gain or loss of function, we discovered that WDR5 promoted bladder cancer cell proliferation in vitro and tumor growth in vivo, and that silencing WDR5 mainly induces the G0/G1 phase cell cycle arrest." (PMID 25656485, 2015). "To study the role of WDR5 in bladder cancer, we created a WDR5 gain or loss of function in bladder cancer cells." (PMID 25656485, 2015). "Through gain or loss of function, we demonstrated that WDR5 promoted proliferation, self-renewal and chemoresistance to cisplatin in bladder cancer cells in vitro, and tumor growth in vivo." (PMID 25656485, 2015). "In addition, WDR5 physically interacts with the BLACAT2 (bladder cancer-associated transcript 2) lncRNA that is markedly upregulated in bladder cancer with lymph node metastasis." (PMID 33302406, 2020). "Recently, OICR-9429, a small molecule inhibitor specifically targeting WDR5, was shown to inhibit the proliferation and reduce the chemosensitivity of bladder cancer cells." (PMID 37783676, 2023). "WDR5, another member of the WD repeat family, has also been found to play a role in the LN metastasis process in bladder cancer." (PMID 37783676, 2023). "In our mass spectrometry analysis, the level of WDR5 in bladder cancer tissues was also found to be increased, but this increase was not as great as the fold increase in the WDR4 level." (PMID 37783676, 2023). "Using genomic data from the cancer genome atlas (TCGA), they found that WDR5 is positively correlated with the expression of PD-L1 in different bladder cancer subtypes." (PMID 38201559, 2023). "Recently, WDR5 was also reported to be involved in lymphatic metastasis in bladder cancer through heat shock factor 1 (HSF1)–protein arginine methyltransferase 5 (PRMT5)–WDR5 axis." (PMID 37568727, 2023). "OICR-9429 blocking WDR5/MLL interaction through binding the core peptide-binding pocket of WDR5 induces cell cycle arrested in G1/S phase and promotes apoptosis and sensitivity to cisplatin in bladder cancer cells." (PMID 36376832, 2022). "Increased levels of the WDR5 protein found in bladder cancer tissues also correlate with advanced tumor stage and poor survival." (PMID 33302406, 2020). "WDR5 has been shown to promote the proliferation of bladder cancer cells by activating the transcription of cyclin genes and the UHMK1 gene in a manner dependent on histone H3 lysine 4 trimethylation." (PMID 33302406, 2020). "The association of WDR5 with BLACAT2 promotes H3K4 methylation and the upregulation of VEGF-C, a lymphangiogenic growth factor, thereby leading to bladder cancer-associated lymphangiogenesis and lymphatic metastasis." (PMID 33302406, 2020). "WDR5 is upregulated in bladder cancer tissues, and high levels of WDR5 expression positively correlate with advanced disease stage and poor patient survival." (PMID 30488017, 2018). "Our study investigated the role of WDR5 in bladder cancer and demonstrated that WDR5 was upregulated in bladder cancer tissues, and elevated WDR5 protein levels positively correlated with advanced tumor stage and poor survival." (PMID 25656485, 2015). "Collectively, these results demonstrate that WDR5 knockdown mainly induces G0/G1 phase cell cycle arrest in bladder cancer cells." (PMID 25656485, 2015). "The overall survival for bladder cancer patients with higher WDR5 expression was significantly shorter than those patients with low WDR5 expression (p = 0.04)." (PMID 25656485, 2015). "To investigate the target genes of WDR5 in bladder cancer, we knocked-down WDR5 by si-WDR5-2 and si-WDR5-3 separately and monitored the changes in mRNA levels by microarray." (PMID 25656485, 2015). "To detect the expression of WDR5 in bladder cancer, we examined WDR5 expression in 134 bladder cancer tissues and 77 normal tissues by immunohistochemistry (IHC)." (PMID 25656485, 2015).
bladder cancer (continued). "Upon clinicopathological correlation analysis, elevated WDR5 protein levels positively correlated with advanced tumor stage of bladder cancer (p = 0.005)." (PMID 25656485, 2015). "We found that WDR5 silencing increased cell apoptosis and decreased bladder cancer cells resistance to cisplatin." (PMID 25656485, 2015). "Taken together, these data indicate that WDR5 regulates target genes in bladder cancer by mediating H3K4me3 levels." (PMID 25656485, 2015). "Most of the bladder cancer tissues (69.4%, 93/134 cases) were found to exhibit high WDR5 expression." (PMID 25656485, 2015). "The log-rank test revealed that WDR5 expression correlated significantly with the overall survival of bladder cancer patients." (PMID 25656485, 2015). "Taken together, our results suggest that WDR5 plays a vital role in self-renewal of bladder cancer cells by regulating Nanog." (PMID 25656485, 2015). "In this study, we found that WDR5 expression was increased in bladder cancer tissues and correlated with advanced tumor stage and poor survival." (PMID 25656485, 2015). "In summary, it is our novel discovery that WDR5 is upregulated in bladder cancer, and promotes bladder cancer cell proliferation, self-renewal and chemoresistance via activating a series of oncogenes by H3K4me3." (PMID 25656485, 2015). "Given that WDR5 regulates various genes in bladder cancer, we identified the target genes of WDR5 by microarray, qPCR and Western blotting." (PMID 25656485, 2015). "Mechanistically, WDR5 regulated various functions in bladder cancer by mediating the transcription of cyclin B1, cyclin E1, cyclin E2, UHMK1, MCL1, BIRC3 and Nanog by histone H3 lysine 4 trimethylation." (PMID 25656485, 2015). "Finally, WDR5 upregulation promotes proliferation, self-renewal and chemoresistance in bladder cancer via H3K4 trimethylation." (PMID 37974198, 2023). "Additionally, WDR5 promotes the cell proliferation, self-renewal and chemoresistance of bladder cancer by activating multiple oncogenes via increasing H3K4me3 levels." (PMID 37741985, 2023). "The lncRNA BLACAT2 is markedly upregulated in metastatic bladder cancer cells, and BLACAT2 upregulates vascular endothelial growth factor C (VEGF-C) expression by binding to WDR5, resulting in bladder cancer-associated lymphangiogenesis and lymphatic metastasis." (PMID 30488017, 2018). "In addition, there are many questions to be elucidated, such as the correlation between WDR5 with metastasis and disease specify survival of bladder cancer patient." (PMID 25656485, 2015). "Therefore, we have discovered that WDR5 plays an important role in bladder cancer suggesting that WDR5 is a potential biomarker and a promising target in the treatment of bladder cancer." (PMID 25656485, 2015). "In sum, these findings indicate that WDR5 enhances bladder cancer cell anti-apoptosis and chemoresistance to cisplatin by regulating MCL1 and BIRC3, and it may be a potential target for drug development." (PMID 25656485, 2015). "In contrast, overexpression of WDR5 enhanced bladder cancer cell viability and colony formation." (PMID 25656485, 2015). "Taken together, high expression levels of WDR5 may serve as a novel molecular marker for bladder cancer." (PMID 25656485, 2015). "Therefore, WDR5 is a potential biomarker for bladder cancer and a promising target for drug development." (PMID 25656485, 2015). "We also found that WDR5 knockdown obviously decreased the expression of H3K4me3, suggesting that WDR5 might regulate target genes in bladder cancer by H3K4me3." (PMID 25656485, 2015). "WDR5 was obviously upregulated in bladder cancer tissues compared with normal tissues." (PMID 25656485, 2015). "Although basic knowledge related to WDR5 has increased recently, the expression pattern and biological function of WDR5 in bladder cancer remains largely unknown." (PMID 25656485, 2015).
bladder cancer (continued). "Because WDR5 and BPTF are necessary for H2A.Z to upregulate gene transcription in the bladder cancer cells, we also check whether they are functionally linked to H2A.Z-induced cell growth." (PMID 24279307, 2013). "LncRNA BLACAT2 directly interacts with WDR5 and promotes H3K4 methylation, which enhances the expression of VEGF-C epigenetically in bladder cancer with lymph node metastasis." (PMID 36471363, 2022). "This study evaluated the role of targeting WD repeat domain 5 (WDR5) with the small molecule compound OICR-9429 and whether it could be used to treat bladder cancer." (PMID 34154613, 2021). "WD repeat domain 5 (WDR5) plays an important role in various biological functions through the epigenetic regulation of gene transcription; however, its role in bladder cancer remains largely unknown." (PMID 25656485, 2015). "Here, we found that WDR5 was upregulated in bladder cancer tissues compared with normal tissues by IHC, and correlated with advanced tumor stage and overall survival of bladder cancer patients." (PMID 25656485, 2015). "Mechanistically, WDR5 up-regulates cyclin B1, cyclin E1, cyclin E2, UHMK1, MCL1, BIRC3, and Nanog gene transcription through inducing histone H3K4 trimethylation, resulting in bladder cancer cell proliferation, self-renewal and chemo-resistance to cisplatin in vitro and tumor growth in vivo." (PMID 30488017, 2018).